RAD51 (RAD51 recombinase)
Diseases named in the same sentence as RAD51 in open-access papers (continued):
Sharing a sentence is not in itself a finding about the gene and the disease.
cancer (continued). "However, Rad51 is overexpressed in cancer cells relative to normal cells and its selective inhibition by RNA interference increases sensitivity to chemotherapeutic killing of human cancer cells relative to normal cells, both in vitro and in vivo." (PMID 25401086, 2014). "However, high level of RAD51 expression in cancer cells may potentially hinder the inhibitory effect of B02." (PMID 24971740, 2014). "Thus it appears that RAD51 has two distinct roles in promoting metastasis; the first is based on the increased repair and stabilizing the cancer genome allowing spread of tumor cells and the second as a regulator of c/EBPβ in promoting pro-metastatic gene expression." (PMID 24811120, 2014). "However it remained unknown whether B02 can sensitize cancer cells in which the expression level of RAD51 is significantly increased compared with normal cells." (PMID 24971740, 2014). "The RAD51 genetic variations may contribute to the development of cancers." (PMID 24457040, 2014). "Hence, inhibition of RAD51 functions may provide an effective approach to cancer intervention, as also shown by earlier studies using RAD51 RNAi or antisense RNA." (PMID 23341130, 2013). "Therefore, small molecule inhibitors of RAD51 may suggest a novel class of broad-spectrum therapeutics for difficult-to-treat cancers." (PMID 23341130, 2013). "Taken together, IBR2 represents the first small molecule that directly binds RAD51, disrupts RAD51 multimerization, inactivates RAD51 functions both in vitro and in vivo, which suggests a novel entry point for developing potential therapies in compliment to current treatments for cancer." (PMID 23341130, 2013). "This, in turn, led to the up-regulation of other homologous recombination repair genes, such as breast cancer type 1 (BRCA1) and DNA repair protein RAD51 homolog 1 (RAD51), contributing to the development of adaptive resistance to olaparib treatment." (PMID 41362671, 2026). "However, pan-cancer analyses of analyzed cancer genomes show a marked absence of RAD51 loss of function mutations leading to a so-called "RAD51 paradox": increased chromosomal instability despite normal RAD51 function." (PMID 42133623, 2026). "Radioresistance arises from cancer stem cell maintenance (CD133/HMGB2), TAM polarization (CSF-1R/CD44), and enhanced homologous recombination (RAD51)." (PMID 42125691, 2026). "Our analysis revealed 9 shared genes, with UBE2C, POLQ, RAD51, and HOXB7 being up-regulated and EDNRB, GPD1L, F10, SORBS2, and CXCL12 down-regulated in both cancers." (PMID 41790655, 2026). "The phosphorylation of SYCP2 by ABL1, which stabilizes R-loops and facilitates RAD51 recruitment, suggests that ABL1 acts as a critical mediator between transcription and DNA repair in cancer cells." (PMID 40918650, 2025). "In our assay, RAD51 and p-RPA2 staining only produces foci if the cancer cells recently experienced HR and replication stress, thereby providing a dynamic reading of both processes." (PMID 40392598, 2025). "Together, population-level in different cancer cell lines, and perturbation data argue for links between SFPQ and RAD51 expression." (PMID 40964404, 2025). "Among the genes closely related to SPSB2 expression, CDC45, RAD51, TRIP13, MYBL2, and CDC20 play essential roles in cancer development." (PMID 40149497, 2025). "In such a scenario, it would be predicted that BRCA-proficient cancer cells need to enhance the activation of homologous recombination factors such as BRCA1, BRCA2, and RAD51 to repair dsDNA breaks." (PMID 40243501, 2025). "Both metrics were analyzed, but AUC remains the gold standard for direct comparison with prior radiomics studies, such as those investigating RAD51, SCN3B, and CDK2 in cancer biomarker discovery." (PMID 40535132, 2025).
cancer (continued). "To further explore mechanisms underlying the reduced efficiency of homology directed repair in FTO knockdown cells, we compared RAD51 foci formation, a marker of active HR repair, in the control and FTO knockdown HNSCC cancer cells before and after RT." (PMID 40485587, 2025). "Including DNA-PKcs, CHK1, CDK12, RAD51, POLθ and WRN, inhibitors of these pathways can provide new opportunities for cancer treatment by inducing synthetic lethality." (PMID 40240755, 2025). "In G401 cells, the depletion of MYC results in a similar decreased level of both ATR and RAD51, suggesting that MYC generally controls DNA repair protein expression in SWI/SNF-altered cancer cell lines, as has been seen in other cancers." (PMID 40647552, 2025). "Initially, we analysed the correlation between mRNA expression levels of RAD51 and its auxiliary protein RAD51AP1 with sensitivity to various anticancer drugs using the Cancer Therapeutics Response Portal (CTRP) database." (PMID 41350246, 2025). "Here we find that melatonin (MT) not only downregulates TRIP13 but also the DNA repair proteins RAD51 and XRCC5, thereby inhibiting aberrant DNA repair in cancer cells." (PMID 41145438, 2025). "Even though limited toxicity is induced, a clear effect on the RAD51 IRIF and BRCA2 protein levels was shown in the normal breast epithelial cell line (MCF10a) and the tested cancer cell lines." (PMID 40647408, 2025). "BBR reportedly down‐regulated the protein RAD51 and impaired DNA HR repair, which indicates the potential off‐target effects of BBR besides LIGIII on the cancer radiosensitivity." (PMID 40916080, 2025). "CTCF depletion leads to the disruption of chromatin organization around the DNA damage sites, which abolishes the recruitment of essential DNA damage repair proteins BRCA2 and RAD51, as well as impairs homologous repair in the IDH mutant cancer cells." (PMID 39920158, 2025). "Since FL118 reduced the survivin–RAD51 levels at lower concentrations than SN38, it should be more effective in combination therapy, with broader applications in cancer treatment." (PMID 39410005, 2024). "Our data, including an HR/NHEJ reporter assay, RAD51 foci, and IHC staining in CDX tissues, demonstrated that NDRG1 enhances HR-mediated DDR in cancer cells." (PMID 38970106, 2024). "Together, these results suggest that, in SYCP2-expressing cancer cells, SYCP2 acts upstream of RAD51 to facilitate RAD51 foci formation upon DNA damage in the HR pathway." (PMID 38383600, 2024). "One compound, RS-1, is especially toxic in cancer cells that express high levels of RAD51 but low levels of RAD54L, a protein that removes RAD51 from dsDNA." (PMID 36980782, 2023). "Substantial variations in both the basal expression (ATR, Claspin, Chk1, and Rad51) and agonist-induced activation (p-Chk1) of DDR components were observed in canine cancer cell lines." (PMID 37655260, 2023). "We observed that the protein levels of FANCD2, RAD51, and ATR, which promote alternative end-joining, DNA damage repair, and cancer cell survival, were downregulated." (PMID 37020276, 2023). "Thus, single-allele deletions of RAD51 and RAD51C appear to be haplo-insufficient in limiting APOBEC-induced mutation, which further supports a model in which HR factors are used to bypass APOBEC-induced abasic sites to reduce APOBEC-signature mutations in multiple human cancer types." (PMID 37532520, 2023). "Since homologous recombination is an essential DNA repair pathway to preserve genomic stability, its inhibition, namely, by targeting ATM, ATR, CHK1, CHK2, WEE1, RAD51 and RAD52, represents a promising therapeutic strategy in cancer treatment." (PMID 38136266, 2023). "Most notably, racial differences between Black and White samples in the expression of genes pertaining to homology-directed repair, including RAD50, RAD51, MRE11, ERCC1, and BRCA2, were observed in five cancer types." (PMID 37345032, 2023).
cancer (continued). "Overall, our findings provide the preclinical rationale to explore RAD51 inhibitors as monotherapy or in combination with chemotherapy, immunotherapy or DDR-targeting therapy in cancer treatment." (PMID 35646698, 2022). "Overexpression of RAD51 enhanced DNA repair HDR activity and helps cancer cells to survive and develop resistance to DNA damaging agents." (PMID 35463312, 2022). "PPI analysis showed potential interactions between three cancer driver genes (AKT1, KRAS, and PIK3CA) and candidate genes (CCNE2, RAD51, and NEIL3)." (PMID 36233194, 2022). "Further structural optimization of IBR2 generated the stereo selective inhibitor IBR20 which also disrupts RAD51 multimerization, impairs HDR activity and increases cytotoxic activity in a variety of cancer cell lines." (PMID 35463312, 2022). "In this study, we further investigated consequences of elevated RAD51 and HR in EAC as well as other cancers." (PMID 36428789, 2022). "Therefore, we sought to examine whether Nanog could inhibit endogenous Rad51 in human cancer cells." (PMID 35220392, 2022). "Therefore, unlike its direct HR partners, RAD51 has not been classified as causal for cancer." (PMID 34316706, 2021). "Another small molecule RAD51 inhibitor, CYT-0851, is currently in a clinical trial as monotherapy against several types of cancer." (PMID 34337349, 2021). "Contrarily, on the other hand, hypoxia reduces the expression of several key HRR effectors such as NBN, MRE11, RAD51, and BRCA1 in different cancer cell models." (PMID 34539584, 2021). "Here, we found that LRRK2 is required for the interaction of RAD51 and BRCA2, which is responsible for the recruitment of RAD51 to DNA damage sites in LRRK2–high‐expression cancer cells." (PMID 33784003, 2021). "Breast cancer 2 (BRCA2) has been shown previously to interact with RAD51 and mediates RAD51-dependent DNA repair." (PMID 34819065, 2021). "However, to date, there has been no case of a patient with FA-R (RAD51 mutation) developing cancer." (PMID 34316706, 2021). "RAD51 is a component of the cellular DDR, and as such, inhibition of RAD51 sensitizes cancer cells to DNA-damaging drugs." (PMID 34408776, 2021). "Specifically, EGFR is a widely studied oncogene with a potential role in cancer therapeutics, six are core genes (AURKA, CDK1, CDT1, PRKDC, RAD51, and XRCC2), six are potential drug targets, and five were identified as drug actionable genes." (PMID 33240468, 2020). "In a previous work from our group, PARP and RAD51 inhibitors, Olaparib (AZD2281) and B02, respectively, were combined in order to sensitise cancer cells to proton irradiation." (PMID 32635552, 2020). "While IHC has been successfully used to detect phospho-specific MYBL2 in human carcinomas, a more feasible approach would be to employ IHC panels detecting MYBL2 and MYBL2-regulated targets such as FOXM1, CHK1, and RAD51." (PMID 33489883, 2020). "In agreement with this notion, a decrease in RAD51 foci after radiation exposure and MMS were observed in transformed human cancer cells upon siRNA knockdown." (PMID 31665741, 2019). "Sensitizing cancer cells to DNA-damaging agents, such as IR, can be achieved by directly targeting key proteins of the DDR, including the ATM and ATR kinases or RAD51 recombinase." (PMID 31993371, 2019). "While it has been known in other cancers that CHD4 goes to sites of DNA damage, we found CHD4 also regulates expression of RAD51, an essential component of the homologous recombination machinery, which repairs DNA damage." (PMID 30872624, 2019).
cancer (continued). "Numerous studies have shown that several cancer cells, including GBM cells as compared to normal cells, have higher levels of RAD51, demonstrating its involvement in resistance to IR and that RAD51 downregulation determined the radiosensitivity." (PMID 31993371, 2019). "In vitro, the RAD51 inhibitor, IBR2, sensitises cancer cells to IR, by disrupting the RAD51–BRC interaction (inducing proteasome-mediated RAD51 degradation)." (PMID 29757235, 2018). "SAHA’s effect on homologous recombination repair was analyzed by Rad51 and RPA foci formation at 3 and 5 h after 1 Gy of γ-ray or proton beam radiation in cancer cell line." (PMID 29414878, 2018). "Together with previous reports of VPA augmented radiation-induced apoptosis through targeted activity on BRCA1, Rad51 and Ku80 proteins, this study advanced the proposal for the use of VPA as a neoadjuvant to radiotherapy for cancer treatment." (PMID 28489060, 2017). "The number of RAD51 foci induced by cisplatin (CDDP) in A2780 and HO8910 cells was significantly reduced when cancer cells were co-treated with berberine." (PMID 28981112, 2017). "In this study, to elucidate the mechanism of DNA repair in oleandrin induced anti-tumor effect, we measured expression of DNA damage repair proteins RAD51 and XRCC1 in oleandrin-treated cancer cells." (PMID 27449097, 2016). "Effectors of HR such as BRCA1 (Breast Cancer 1), BRCA2, MRE11A and RAD51 were significantly expressed following IR." (PMID 27495836, 2016). "This pathway is a genetic disease about DNA repair genes–BRCA1, RAD51, PMS2 and FANC proteins–which are higly related to cancers." (PMID 27883053, 2016). "Thus, targeting RAD51 could increase the effectiveness of cancer treatments." (PMID 26910887, 2016). "In addition, our study may improve the understanding of the regulatory roles of miRNA variants of RAD51 3′UTR in its mRNA expression and the translation of pharmacogenetic predictors into clinical practice may lead to improved cancer treatment planning and outcome." (PMID 27733989, 2016). "There are already a precedent for the roles of unregulated CDC20, RAD51, and CHEK1 in cancer development and progression." (PMID 25763370, 2015). "In turn, the importance of Rad51 in the HR pathway is highlighted by the tumor suppressor protein BRCA2, which is involved in breast and ovarian cancers, as well as other types of cancers." (PMID 25938495, 2015). "Among these genes, it is worth to notice the presence of important cancer genes such as E2F1, E2F2, and RAD51, which combined starvation and crizotinib down-regulated to a higher extent compared to these treatments alone." (PMID 25909220, 2015). "In particular inhibitors to DNA-PKs (NHEJ), RAD51 (HR), PARP1/2 (HR, altNHEJ, BER), CHK2 (HR, altNHEJ), CHK1 (HR, NER) are currently under clinical investigation in various cancers." (PMID 24809299, 2014). "Using tail vein assay of cancer metastasis in MDA-MB231 cells, we show that RAD51 dramatically promotes appearance of lung metastasis." (PMID 24811120, 2014). "It was reported that RAD51 overexpression contributes to chemoresistance in human soft tissue sarcoma cells and rescues radiation sensitivity of BRCA2-defective cancer cells." (PMID 24971740, 2014). "Similar to RAD51, several other HR proteins including XRCC3, RAD52 and RAD54 show a 2 to 5-fold increase in mRNA and protein levels in cancer cells indicating an important role of the entire HR pathway in tumorigenesis." (PMID 24971740, 2014).
cancer (continued). "Therefore, a Rad51 inhibitor could serve as a potential adjuvant for cancer therapy." (PMID 22691778, 2012). "Since hypomorphic mutations in RAD51 in mammalian cells also reduce DSB repair by conservative gene conversion and stimulate non-conservative repair by SSA, this mechanism may also operate in humans and, perhaps contribute to the genome instability that propels the development of cancer." (PMID 20686691, 2010). "Because YAP/TAZ-TEAD transcriptional activity governs RAD51 expression in cancer cells, whether SOX5 inhibition regulates YAP and the HR repair genes, BRCA1 and RAD51, in olaparib-resistant cells was investigated." (PMID 40274769, 2025). "High RAD51 expression predicted poor prognosis in OSCC and other cancers." (PMID 41350246, 2025). "miR-7-5p/ABCC1/SLC7A5, miR-107/RAD51, miR-124-3p/ABCC4/SLC16A1/MGMT, miR-212-3p/ABCG2, miR-381-3p/GJA1 and miR-485-3p/SLC40A1 may modulate pathways that confer chemoresistance to cancer cells." (PMID 40061896, 2025). "The involvement of factors like RAD51 and the ATRX/DAXX complex suggests that further elaboration of this pathway could provide critical insights into how ALT-positive cancers maintain their proliferative capacity." (PMID 39858038, 2025). "Notably, the pan‐cancer DSS and PFI survival analyses of RAD51 uniformly indicated poor prognosis, whereas only the OS analysis suggested a favourable prognosis in two cancer types." (PMID 41350246, 2025). "Finally, leveraging the Genomics of Drug Sensitivity in Cancer (GDSC) and CTRP databases, we identified compounds whose sensitivity positively correlated with RAD51 expression, suggesting their potential utility for targeting RAD51 in OSCC therapy." (PMID 41350246, 2025). "Consistent with previous findings that greater clonal diversity has been associated with a higher likelihood of therapy-resistant and metastatic subpopulations, we found that patients with heterogeneous RAD51 and p-RPA2 staining in their cancers exhibited the worst survival outcomes." (PMID 40392598, 2025). "Furthermore, HELLS-deficient cells display synthetic lethality with inhibition of RAD51, highlighting the potential therapeutic value of targeting HELLS in cancer." (PMID 41297801, 2025). "Expression of innate immune system markers (APOBEC3A/B), DNA repair genes (BRCA1, BRCA2, PALB2, RAD51), cell cycle genes (CCNA2 and CCNE1), a cell proliferation gene (MELTF), and a T-cell regulator (Treg) marker (FOXP3) was elevated in cancer compared to precancer and controls." (PMID 39672307, 2024). "Besides, several proteins were involved in the regulation of DNA damage repair, including PCNA and RAD51, consistent with the significant correlation between dMMR and high TMB in cancer." (PMID 36911742, 2023). "In addition, a small-molecule radiosensitizer YTR107 was found to suppress SUMOylated NPM1 from interacting with RAD51, resulting in impaired DSB repair and reduced radioresistance of cancer cells." (PMID 37108815, 2023). "This is similar to recent preclinical studies reporting that inhibiting different tyrosine kinase receptors or their downstream signaling transducers can sensitize cancer cells to PARPis by reducing expression of BRCA1, BRCA2, RAD51, and other HR components, thereby preventing HR repair." (PMID 37550562, 2023). "Furthermore, correlation analysis of cancer cell lines from Cancer Cell Line Encyclopedia (CCLE) data showed that LSD1 mRNA expression was positively correlated with BRCA1/2, and RAD51 mRNA expression." (PMID 37973845, 2023). "This is also the first report demonstrating the association of MRE11 rs2155209, XRCC5 rs828907, LIG4 rs1805388, ATM rs1801516 and RAD51 rs12593359 with survival in HNSCC, as well as the first to indicate that CHEK1 rs558351 may play a role in cancer disease." (PMID 37894339, 2023). "Surprisingly, despite its central role in HR, the invalidation of RAD51 is not classified as being cancer prone, constituting the “RAD51 paradox”." (PMID 37190078, 2023).